CPNE3 (copine 3)
Description:
Calcium-dependent phospholipid-binding protein that plays a role in ERBB2-mediated tumor cell migration in response to growth factor heregulin stimulation.
Synonyms: CPN3; PRO1071
Tractability: Antibody: UniProt places it where antibodies can reach, with high confidence; its Gene Ontology location is reachable by antibodies, with high confidence. PROTAC: ubiquitination databases record sites on it; its protein half-life has been measured.
Gene: Protein-coding gene on chromosome 8 (86,514,435 to 86,561,498, forward strand). Ensembl gene ENSG00000085719.
Subcellular location: Nucleus; Cytoplasm; Cell membrane; Cell junction; Cell junction, focal adhesion
Subcellular location (Human Protein Atlas): Cytosol; Nucleoplasm
Pathways (Reactome):
Immune System: Neutrophil degranulation
Metabolism: Glycerophospholipid biosynthesis
Gene Ontology:
Molecular function: calcium-dependent phospholipid binding; calcium-dependent protein binding; protein binding; protein serine/threonine kinase activity; receptor tyrosine kinase binding; RNA binding; protein-membrane adaptor activity
Biological process: cellular response to calcium ion; cellular response to growth factor stimulus; ERBB2 signaling pathway; positive regulation of cell migration; glycerophospholipid biosynthetic process
Cellular component: anchoring junction; cell junction; cytoplasm; cytosol; extracellular exosome; focal adhesion; nucleoplasm; nucleus; plasma membrane; azurophil granule membrane
Genetic constraint (gnomAD): Loss-of-function variants: 33 observed, 31.78 expected, observed/expected ratio (o/e) 1.04, 90% interval 0.79 to 1.39. The upper end of that interval is the gene's LOEUF score, 1.39, which puts it in group 5 of 6, group 1 being the genes least tolerant of losing a copy. Missense variants: 314 observed, 313.13 expected, observed/expected ratio (o/e) 1, 90% interval 0.91 to 1.1. Synonymous variants: 107 observed, 108.62 expected, observed/expected ratio (o/e) 0.99, 90% interval 0.84 to 1.16.
Homologues: Orthologues: chimpanzee CPNE3 (99% identical), macaque CPNE3 (99% identical), dog CPNE3 (96% identical), pig CPNE3 (94% identical), mouse Cpne3 (94% identical), rabbit CPNE3 (92% identical), rat Cpne3 (92% identical), guinea pig CPNE3 (91% identical), tropical clawed frog cpne3 (81% identical), zebrafish cpne3 (76% identical). Paralogues in human: CPNE1 (66% identical), CPNE2 (63% identical), CPNE7 (56% identical), CPNE4 (56% identical), CPNE5 (53% identical), CPNE6 (53% identical), CPNE8 (53% identical), CPNE9 (50% identical).